CD4 (CD4 molecule)
Diseases named in the same sentence as CD4 in open-access papers (continued):
Sharing a sentence is not in itself a finding about the gene and the disease.
tumor (continued). "PD-L1 is a ligand for PD-1, which is a known checkpoint inhibitor of CD4+ T cells that plays important roles in diminishing anti-tumor immunity." (PMID 37781372, 2023). "Lysosomal processing and presenting on MHC II of acquired exogenous antigen by tumor cells were considered to be the major antigen presentation pathway of human CD4+ T cells." (PMID 37287989, 2023). "Previous researches have shown that the high abundance of tumor-associated lymphocytes, like CD8+ T cell, CD4+ T cell, and NK cell, have a positive impact on the prognosis of GC by enhancing the antitumor response." (PMID 37351275, 2023). "Cancer development often entails an excess of host immune tolerance generated by regulatory T-cells, also known as "Tregs" (typically CD4 + FoxP3 + T-cells), over effector CD8 + and CD4 + Foxp3- anti-tumor T-cells in the tumor microenvironment." (PMID 38057799, 2023). "Such as, Activin-A can enhance the anti-tumor ability of the body by preventing the depletion of CD4 T cells." (PMID 37274740, 2023). "As co-receptors of TCR, CD4+ or CD8+ cells can recognize MHC-II molecules on the surface of tumor cells or APC, respectively, and these two molecules can act as the first signal of T cell activation to activate T cells through the MHC-I pathway." (PMID 36872320, 2023). "They detect tumor antigens by detecting MHC class I deficiencies in tumor cells or via the uptake of antigens by dying tumor cells, which activates CD4+ T cells via the T-cell receptor (TCR), CD28, and B-cell responses." (PMID 37894479, 2023). "Our discovery of CD38 and CD39 expression on the surface of cytotoxic tumor-specific CD4+ T cells will allow the identification and isolation of this cell type for future studies and clinical trials relating to CD4+ T-cell specific immunotherapies." (PMID 36869048, 2023). "Strengthening this idea, we have described an immunomodulating effect of the GS-PTX-HA treatment, modifying subpopulations of immune cells including CD4+ T lymphocytes and NK cells in the tumor-draining lymph nodes and in the spleen, respectively." (PMID 36834958, 2023). "This suggests a dual role of CD4+ CTLs in either promoting or suppressing tumor immunity, although the latter function is more prominent in OSCC." (PMID 38077321, 2023). "The main goal of TILs therapy is to restore anti-tumor immunity by an in vitro selection of immune cell populations that are tumor specific, such as CD4+ and CD8+." (PMID 36831480, 2023). "In both tumor models, the F4/80+ area was mostly present in the tumor edge and the nearby skin, whereas CD4+ cells were predominantly found at the tumor edge." (PMID 37304301, 2023). "ACM derived from OGJ patients with early-stage tumours significantly increased the expression of CD27 on the surface of CD4+ T cells compared with untreated cells (untrx: 41.00 ± 3.5 vs. early-stage: 57.55 ± 5.0%, p = 0.01)." (PMID 36790524, 2023). "Specifically, the adoptive transfer of CD4+ T cells or CD4+ CAR T cells can induce tumor regression and a reduction in chronic viral infections, and these cells display both cytotoxicity and polyfunctionality." (PMID 37829505, 2023). "A study also reported that intratumoral injection of sTRAIL suppresses murine hepatoma cell growth by inducing tumor-infiltrating CD4+CD25+ Treg apoptosis." (PMID 37605148, 2023). "The increased frequency of CD4+ compared with CD8+ M1xx CAR T cells found within ovarian tissue of SKOV-3 inoculated mice supports the key role of CD4+ CAR T cells in tumor control." (PMID 36746513, 2023). "The EGFR inhibitor erlotinib reduced CD4+ effector regulatory T-cell infiltration in the tumor microenvironment and showed better antitumor effects in combination with αPD-1 monoclonal antibody than either treatment alone." (PMID 36892747, 2023).
tumor (continued). "It has been reported to be associated with promoted intra-tumor infiltration of immune cells, T-cell accumulation, recruitment of activated CD8+ cytotoxic T and CD4+ T-helper cells, delayed ascites formation, and improved survival." (PMID 37112810, 2023). "To understand why the tumors were smaller in Cd4;Tcf7fl/fl mice, we performed immunohistochemical (IHC) and co-IF analysis of the 7940b tumor tissues." (PMID 36239683, 2023). "Additional FACS analysis of tumor CD45 + cells showed a decrease in CD4 + CD3 + cells (p < 0.05) in tumors from the SX-682 chow-fed mice." (PMID 37270599, 2023). "In marked contrast, CD8α depletion inhibited the significant eMSC-mediated increase in primary tumor CD4+ T-cell percentages." (PMID 37928528, 2023). "More recently, an immune-modulatory role of IL11 has been reported through its suppressive effect on host CD4+ T cells in the tumor microenvironment." (PMID 37365574, 2023). "The abundance of CXCL13+ CD4+ T cells, the tumor antigen‐specific T cells to immune‐checkpoint blockade, was significantly higher in primary tumors, and a subset of CD4+ T cells had high expression levels of several cytotoxic genes, including GZMB and GZMK." (PMID 37743226, 2023). "Surgical resection of the solid tumor partially revives immune competency, with both CD4+ T cells and CD8+ T cells implicated in re-establishing tumor immunity." (PMID 37746283, 2023). "We found a small population of tumor-infiltrating CD8 (~10% of total T cells on average) together with CD4 helper and regulatory CD4+/FoxP3+ T cells (<50% of total CD4+ T cells) in Renca tumors." (PMID 38259453, 2023). "The reprogrammed cancer cells then present the tumor antigens to CD4+ Tfhs via MHC-II and release CX3CL1 to recruit NK cells, PMos and cDC2s." (PMID 36869384, 2023). "In the NACRT group, a very high Ki67 index (≥90%, p = 0.03) and higher tumor infiltration by T cells (the sum of CD8+ and CD4+ cells) (p = 0.05) were markedly associated with pCR." (PMID 37046691, 2023). "This fact enables cancer cells to directly present tumor neoantigens to CD4+ T cells, providing their activation in the tumor microenvironment (TME) in an APC-independent manner." (PMID 37761972, 2023). "In CHOL, UCEC, PACA, and ESCA, the tumor infiltrating CD4+ T cells are more likely to develop along Treg path rather than Temra path." (PMID 36641532, 2023). "For instance, the depletion of αSMA+ myofibroblasts in PDAC suppressed tumor immune surveillance with an increase in the percentage of regulator T cells (Treg, CD4+Foxp3+), which led to aggressive tumor progression and reduced animal survival." (PMID 37784082, 2023). "CXCL1 also induces the recruitment of naive CD4+ T cells, which are transformed into regulatory T (Treg) cells under the influence of the tumor microenvironment." (PMID 37108425, 2023). "TTS (C215Fab-SEA) treatment induced massive tumor infiltration of CD4 + and CD8 + T cells, while only scattered T cells were observed in untreated tumors." (PMID 36967382, 2023). "Exhausted or dysfunctional CD8+ and CD4+ T cells are frequently programmed to solicit B-cell help in the face of tumor persistence." (PMID 37025597, 2023). "Mice receiving adjuvant NIPP treatment after surgical resection of orthotopic breast cancer tumors showed an increased percentage of mature CD86+ and CD80+ DCs in tumor-draining lymph nodes, and increased numbers of tumor-infiltrating CD4+ and CD8+ T cells." (PMID 36831415, 2023). "OXP significantly increased immune cells infiltration and alters the cell surface markers of infiltrating CD4+ T cells and DC cells, which contributed to improving the anti-tumor effect and the treatment response of ICIs." (PMID 36960067, 2023). "CD4+ CD25+ T regulatory cells (Treg) are immunosuppressive cells that enhance tumor growth, and they are considered one of the main immunotherapeutic targets for cancer." (PMID 37686159, 2023).
tumor (continued). "Amongst other infiltrating immune cell types, it is widely known that the IDH mutation leads to drastically altered tumor immunology, notably decreased CD8 and CD4 T-cell numbers and infiltration into the tumor tissue compared to IDH-wild type cases." (PMID 37509387, 2023). "These cell therapy studies clearly demonstrated the clinical relevance of tumor antigen-specific CD4+ T cells in treatment of different cancers." (PMID 37965314, 2023). "They found that tumor-related CD4+T cell clones had higher cytotoxicity than their CD8+T counterparts." (PMID 37671151, 2023). "Deeper analysis revealed a pronounced upregulation of CD4+ T cells, CD8+ T cells, dendritic cells, and macrophages in the low-risk group, indicating an active and enhanced immune response within their tumor microenvironment." (PMID 38169731, 2023). "In tumor immune responses, CD4+ T cells can activate CD8+ T cells through a variety of mechanisms, so that CD8+ T cells can differentiate into cytotoxic T lymphocytes while maintaining and strengthening the antitumor response." (PMID 38106403, 2023). "Circulating immune cells: Many studies seeking to understand the impact of thermal ablation on tumor immunity have examined its effects on peripheral blood immune cells, including CD4+ T cells, CD8+ T cells, and DCs." (PMID 38022658, 2023). "While CD8+ TILs isolated from MC38 tumours displayed well-defined phenotypes, CD4+ TILs were highly heterogenous and difficult to define in this study." (PMID 37153625, 2023). "Another question that remains to be addressed regards the identity of MHC class II-restricted tumour antigens recognised by CD4+ T cells in the MC38 model." (PMID 37153625, 2023). "CD4+T cells can eliminate tumor cells directly through the mechanism of cytolysis, they can also indirectly attack tumor cells by regulating the tumor TME." (PMID 37274740, 2023). "CD4+ T cells can differentiate into a variety of helper T cells (Th) and regulatory T cells (Tregs) in different tumor environments." (PMID 37869003, 2023). "Treg cell depletion has shown promising results in preclinical cancer models, and anti-CTLA-4 therapy not only increases tumor-specific effector CD4+ T cells but also depletes intratumoral CTLA-4+ Tregs." (PMID 37346034, 2023). "The important role of antigen presentation via the MHC-II pathway in MPR patients was also demonstrated by CD20+ B cells and cDC2s presenting tumor antigens to CD4+ T cells by MHC-II." (PMID 36869384, 2023). "HLA-DR is one of three MHC class II glycoproteins expressed on antigen-presenting cells whose function is to present tumor peptide antigens to the T-cell receptors on CD4+ T cells resulting in cellular activation." (PMID 36830562, 2023). "The utilization of αGITR antibodies to mitigate Tregs functionality has been discovered to induce the differentiation of CD4+T cells into effector T cells, diminish Tregs-mediated immune suppression, and generate anti-tumor impacts." (PMID 38089966, 2023). "T helper (Th) cells, also known as CD4+ T cells, can suppress tumor growth through secreting proinflammatory cytokines, such as IFN-γ." (PMID 37426671, 2023). "Massive IFN−ɤ after restimulation with a CD4 epitope indicates a Th1 memory, a key player in the activation and maintenance of an anti-tumor immunity." (PMID 37727790, 2023). "Dynamics in NRs during treatment were dominated by a decrease in tumour cell populations (C1-2, C4-6), decreases in the CD4+ cell population (C7) and an increase in one CD8+ cell population (C19)." (PMID 37090678, 2023). "Optimization of combination therapies that effectively target CD4+Treg while enhancing anti-tumor immune responses represents a promising avenue for the improved treatment of cancer." (PMID 38250084, 2023). "To assess the contribution of T cells to tumor regression, we used Cd4-iDTR mice to enable inducible ablation of T cells during bacterial treatment." (PMID 36821387, 2023).
tumor (continued). "As reported, CD4+ T cells can function as tumor growth suppressors and induce cytolysis by secreting interferon-γ (IFN-γ)." (PMID 37741993, 2023). "The normal samples had a higher proportion of native B, resting memory CD4+ T, resting mast, and resting dendritic cells than the tumor samples." (PMID 37670814, 2023). "This is achieved via early initiation of a CD4+/Treg–skewed T cell response, and we provide evidence that the tumor-derived Wnt modulator DKK3 is critical to this process." (PMID 37847565, 2023). "Similar to splenic T cells, tumor-derived CD4 T cells were enriched by HT-29 co-culture, whereas tumor CD8 T cells did not expand, again suggesting either their dysfunction or lack of tumor-reactive T cell clones." (PMID 37185301, 2023). "We also reported that stroma-derived ANGPTL2 contributes to tumor suppression via macrophage-mediated CD4+ Th1 cell anti-tumor responses." (PMID 37736764, 2023). "High-affinity MHC-I-restricted TCRs can, however, display CD8 co-receptor independence and mediate anti-tumor reactivity when expressed in CD4+ T cells." (PMID 37849763, 2023). "The low-risk group had more infiltration of immune cells (B cells, CD8+ T cells, CD4+ T cells), mainly with anti-tumor immune function (p < 0.05)." (PMID 36672493, 2023). "To explore the molecular mechanism of CD4-mediated killing, we examined the expression of cytotoxic molecules on CD4 T cells after HT-29 co-culture and tested the functional requirement of cytotoxic activity in killing the tumor cells." (PMID 37185301, 2023). "Combining S100 with αTim-3 effectively promoted cDC2 maturation and antigen presentation, releasing CD4+ T cells, thus reducing tumor burden while prolonging survival." (PMID 37771774, 2023). "Serum zinc concentration, average area per tumor, colon length, and mouse body weight were similar to those before removal of CD4- and CD8-positive cells." (PMID 37298408, 2023). "CD4+ T cells part of the adaptive immune system play a crucial role in regulating an antigen-specific immune response against the tumor." (PMID 36672677, 2023). "Regulatory T cells CD4+CD25+CD3+ are abundant in the tumor mass and the malignant ascites of OC patients with later stage disease, and they suppress the production of IFN-γ and IL2 and subsequent T cell activation." (PMID 37445860, 2023). "Pharmacological blockade of A2aR by SCH58261 delayed the tumour growth in the HNSCC mouse model and significantly decreased the population of CD4+Foxp3+ Tregs and enhanced the anti-tumour response of CD8+ T cells." (PMID 36445478, 2023). "The density of Cd4+ and Cd8+ T cells in tumor cells and spleens was improved by combined treatment compared with anti-PD-1 antibodies." (PMID 37330579, 2023). "Splenic CD4+ T cells also increased significantly following Huaier administration in tumor-bearing mice leading to marked elevation of CD4+/CD8+ ratio." (PMID 37449208, 2023). "In a hypodermic CT26 tumor model, CD4+ Foxp3+ Treg cells are the predominant immunosuppressive cells." (PMID 37152373, 2023). "HCC patients had a greater ratio of Th1 to CD4+ T cells than that in healthy controls, and patients with a higher tumor-infiltrating Th1 cell count have a considerably longer lifetime." (PMID 37509488, 2023). "G-CSF/G-CSFR increased the secretion of FoxP3-expressing CD4+ and CD8+ T cells, while G-CSFR deficiency in T cells increased cytotoxic activity in the tumor microenvironment by producing IL-17A which improved resistance to anti-PD-1 therapy." (PMID 37875976, 2023). "The subpopulation of CD4+ T cells, Treg cells, can mediate an immunosuppression to inhibit effector T cells function, thereby inducing tumor progression and chronic viral persistence." (PMID 37829505, 2023). "In line with our previous results, the TME in the tumor-clearing phase was dominated by CD4 T cells, whereas CD8 and regulatory T cell infiltration were markedly decreased." (PMID 36774352, 2023).
tumor (continued). "Although CD8+ T cells recognizing epitopes derived from oncogenes mediate direct cytotoxicity against tumor cells, the role of CD4+ T cells in antitumor immunity is less well understood." (PMID 36512410, 2023). "Given the limited need for CD4 T cells to generate concomitant immunity, we compared the ability of a potent vaccine versus tumor implantation to protect against distant tumor challenge." (PMID 37072485, 2023). "The levels of tumor CD8+ T cells, tumor PD-1+CD4+, and tumor PD-1+CD8+ T cells remained lower than those in stromal cells both at baseline and during combination treatment." (PMID 37275884, 2023). "The follicular lymphoma immune tumor microenvironment was enriched for memory and naïve CD4+ and CD8+ T cells, B cells, monocytes/macrophages, and endothelial cells." (PMID 36414691, 2023). "The expression of five markers (CD3/CD4/CD8/CD19/CD163) of tumor immune cells was evaluated retrospectively in tumor sections from 68 consecutive cases of TNBC by immunohistochemistry." (PMID 37090736, 2023). "Surprisingly, immunization with necroptotic cells stimulated an anti-tumor CD4+ T cell response while CD8+ T cells were dispensable for tumor protection." (PMID 38196632, 2023). "Consistent with results from splenic T cells, CD4 T cells from regressing tumors showed HT-29 tumor-specific killing." (PMID 37185301, 2023). "As exemplified here, understanding how tumor-intrinsic factors influence mechanisms of CD4+ T-cell activity represents an important step for leveraging the unique contributions of CD4+ and CD8+ CAR T cells for personalized medicine." (PMID 37248395, 2023). "The percentage of Treg within total CD4 T cells gradually reduced from tumor core to distal region among all sites, demonstrating an enrichment of Treg within tumor cores." (PMID 37768208, 2023). "Noteworthy, we observed high upregulation of similar genes in the comparison tumor periphery vs. PBMC for CD4+ T cells as for CD8+ T cells." (PMID 38127790, 2023). "This led to the accumulation of tetanus toxoid proteins within the tumor cells, introduction of tetanus toxoid protein CD4 T cells into the TME, and production of anti-tumor substances." (PMID 37854883, 2023). "Multiple lines of clinical evidence have revealed an important role of the CD4/HLA-II axis in tumor control." (PMID 37185301, 2023). "Consistent with observations in human CRC, these data demonstrate that the progression of MC38 tumours is characterised by increased infiltration of CD4+ and CD8+ TEM cells (as a proportion of total CD4+ and CD8+ T cells)." (PMID 37153625, 2023). "Cytotoxic CD4+ subsets are clonally expanded in bladder tumors, possibly due to tumor antigen recognition." (PMID 38328405, 2023). "Compared to the 2 mg/kg protein treatment group, 8 mg/kg shTRAIL treatment not only significantly increased CD4+ T cells, Tregs, and M2 macrophages in the tumor but also upregulated IL-10 expression in intratumoral M2 macrophages." (PMID 37605148, 2023). "For example, changes in multiple pro-immune cell populations were observed at 7d in the index tumor a substantial distance from the periablational rim, including increased DCs (CD11c), Th1 (CD4+) and CTL infiltration (CD8+) and CTL activity (Fas-L+)." (PMID 37883367, 2023). "Perturbations of GRM4 strengthened the anti-tumor immunity by activating NK, CD4(+) T, and CD8(+) T cells." (PMID 37215113, 2023). "Apart from primary tumors, tumor-specific cytolytic CD4 T cells have been shown to be important for control of lung tumor metastases." (PMID 37654482, 2023). "Recruitment of immune-suppressive Tregs and interestingly, polarizing effector CD4+ T cells to pro-tumor Treg subset demonstrates the immune-modulatory feature of the TME." (PMID 38038865, 2023). "CD4+ regulatory T cells (Tregs) expressing the transcription factor FoxP3 promote tumor progression by effectively suppressing anti-tumor immunity, and scRNA-Seq identified many genes associated with Tregs." (PMID 36769267, 2023).